SLC12A2-DT (SLC12A2 divergent transcript)
Synonyms: FLJ33630; LINC01184
Gene: Long non-coding RNA gene on chromosome 5 (127,939,152 to 128,083,974, reverse strand). Ensembl gene ENSG00000245937.
Diseases named in the same sentence as SLC12A2-DT in open-access papers:
SLC12A2-DT is named in the same sentence as 7 diseases in open-access papers, as found by Europe PMC text mining. Sharing a sentence is not in itself a finding about the gene and the disease. The quoted sentences say what the papers report.
bladder cancer (1 paper, 2022). "The results showed that PCAT7 and UBE2Q1-AS1 LncRNA genes were lowly expressed in human bladder cancer tissues, while LINC01184 (SLC12A2-DT), MPP7-DT, FAM87B were expressed to a great extent in human bladder cancer tissues." (PMID 36454396, 2022). "Five commonly used CRLs were selected for experimental verification by qRT-PCR, including PCAT7, LINC01184 (SLC12A2-DT), MPP7-DT, FAM87B and UBE2Q1-AS1 in human bladder cancer tissues and normal bladder tissues (Normal bladder tissues are assigned to the low-risk group)." (PMID 36454396, 2022).
SLC12A2-DT also shares sentences with these, for which no sentence is quoted: cancer (2 papers); colorectal cancer (2); hepatocellular carcinoma (1); Obesity (1); skin infection (1); tumor (1).